BBS10 (Bardet-Biedl syndrome 10)
Description:
Probable molecular chaperone that assists the folding of proteins upon ATP hydrolysis. Plays a role in the assembly of BBSome, a complex involved in ciliogenesis regulating transports vesicles to the cilia. Involved in adipogenic differentiation.
Synonyms: C12orf58; FLJ23560
Tractability: PROTAC: ubiquitination databases record sites on it.
Gene: Protein-coding gene on chromosome 12 (76,344,474 to 76,348,437, reverse strand). Ensembl gene ENSG00000179941.
Subcellular location: Cell projection, cilium
Pathways (Reactome):
Organelle biogenesis and maintenance: BBSome-mediated cargo-targeting to cilium
Gene Ontology:
Molecular function: protein binding; RNA polymerase II-specific DNA-binding transcription factor binding; ATP binding
Biological process: chaperone-mediated protein complex assembly; non-motile cilium assembly; photoreceptor cell maintenance; regulation of protein-containing complex assembly
Cellular component: cilium
Genetic constraint (gnomAD): Loss-of-function variants: 15 observed, 16.27 expected, observed/expected ratio (o/e) 0.92, 90% interval 0.62 to 1.42. The upper end of that interval is the gene's LOEUF score, 1.42, which puts it in group 5 of 6, group 1 being the genes least tolerant of losing a copy. Missense variants: 858 observed, 894.47 expected, observed/expected ratio (o/e) 0.96, 90% interval 0.91 to 1.01. Synonymous variants: 294 observed, 320.59 expected, observed/expected ratio (o/e) 0.92, 90% interval 0.83 to 1.01.
Gene-disease validity (ClinGen):
ClinGen rates the evidence that BBS10 causes each of these diseases.
BBS10-related ciliopathy (autosomal recessive): Definitive. Any ciliopathy caused by variants in the BBS10 gene.
Homologues: Orthologues: chimpanzee BBS10 (99% identical), macaque BBS10 (93% identical), rabbit BBS10 (76% identical), pig BBS10 (75% identical), guinea pig BBS10 (73% identical), dog BBS10 (72% identical), mouse Bbs10 (67% identical), rat Bbs10 (66% identical), tropical clawed frog bbs10 (33% identical), zebrafish bbs10 (7% identical).